ECT2 (epithelial cell transforming 2)
Diseases named in the same sentence as ECT2 in open-access papers (continued):
Sharing a sentence is not in itself a finding about the gene and the disease.
glioma (continued). "Furthermore, GINS2 regulated the malignant phenotype and TMZ sensitivity of glioma cells, mostly by promoting DNA damage repair by affecting the mRNA stability of early growth response factor 1 (EGR1), which in turn regulates the transcription of epithelial cell-transforming sequence 2 (ECT2)." (PMID 38467631, 2024).
colorectal cancer (9 papers, 2013 to 2025). A primary or metastatic malignant neoplasm that affects the colon or rectum. "In patients with colorectal cancer, high expression level of ECT2 was significantly associated with tumor size, serum CEA levels and TNM stage." (PMID 29088286, 2017). "In this study, we are the first group to evaluate the early diagnostic role of ECT2 in circulating colorectal cancer cells in the peripheral blood." (PMID 28362321, 2017). "Moreover, “amplification” was the dominant form of genetic alteration in most of the analyzed human tumors, except for melanoma and colorectal cancer, which exhibited “mutation” as a dominant ECT2 genetic alteration." (PMID 37106813, 2023). "Colorectal cancer is another form of human cancer where upregulation in ECT2 expression predicts an unfavorable prognosis." (PMID 37106813, 2023). "In this study, we focused on the role of ECT2 expression level in CTCs of colorectal cancer patients." (PMID 28362321, 2017). "A bioinformatic analysis of 34 candidate marker genes of multiple case-matched normal and colorectal tumor tissues identified ECT2 mRNA as a potential colorectal cancer biomarker." (PMID 28362321, 2017). "We observed that the expression of ECT2 can therefore serve as an alternative measurement that can compensate for the inadequacy of the current CEA test in colorectal cancer patients." (PMID 28362321, 2017). "Nevertheless, our present results revealed that ECT2 in peripheral blood could be a biomarker for predicting CTCs in colorectal cancer patients." (PMID 28362321, 2017). "However, further study that includes a larger study population should be conducted to confirm the role of ECT2 in predicting the presence of CTCs and poor prognosis in colorectal cancer patients." (PMID 28362321, 2017). "ECT2 has been found to be up-regulated during transition to malignancy in a mouse model, to be amplified and overexpressed in non-small cell lung cancer, and to have an elevated expression in colorectal cancer." (PMID 23382830, 2013). "Colorectal cancer patients with low tumor/normal expression ratios had more advanced lymphatic invasion than did patients with high expression ratios, which suggested that tumors that express high levels of ECT2 might have lower invasion capability." (PMID 28362321, 2017). "The expression of ECT2 can therefore serve as an alternative measurement that can compensate for the inadequacy of the current CEA test in the diagnosis and monitoring of colorectal cancer patients." (PMID 28362321, 2017). "Significantly higher mRNA expression of ECT2 was detected in the peripheral blood from colorectal cancer patients than from the non-cancer donors (mean of ECT2 expression: 0.97 vs. 1.88, normal vs. patients, p = 1.42 × 10−15)." (PMID 28362321, 2017). "Thus, ECT2 expression can be considered as an alternative measure that can compensate for the inadequacy of the current CEA test for monitoring and prognosis of colorectal cancer patients." (PMID 28362321, 2017).
lung squamous cell carcinoma (9 papers, 2016 to 2024). "We previously reported that a PRKCI-ECT2 signaling activity score, calculated from a lung squamous cell carcinoma PKCι-ECT2-signaling-dependent gene signature, predicted poor survival of patients with numerous cancer types, including PDAC." (PMID 35159064, 2022). "ECT2 is found to be upregulated in lung adenocarcinoma and lung squamous cell carcinoma, as well as in invasive breast cancer." (PMID 31277598, 2019). "There were repeat copies of PIK3CA and ECT2 in approximately 45% of patients in a TCGA lung squamous cell carcinoma cohort." (PMID 27029057, 2016). "The co-amplification of FXR1, protein kinase C, iota (PRKCI), and epithelial cell transforming 2 (ECT2) is detected in lung squamous cell carcinoma (LSCC) tissues; biologically, Fxr1 forms a complex with PRKCI and ECT2 to promote cell proliferation and invasion." (PMID 35565262, 2022). "For example, most (> 90%) of LSCC (Lung Squamous Cell Carcinoma) tumors exhibit an increase in copy number at chromosome 3q26, resulting in the upregulation of the PRKCI, SOX2, and ECT2 oncogenes and LSCC tumorigenesis." (PMID 38504159, 2024). "In this study, we explored the mechanisms of ECT2 dysregulation and compared its prognostic value in lung adenocarcinoma (LUAD) and lung squamous cell carcinoma (LUSC)." (PMID 29088286, 2017). "Another recent study assessed the prognostic value of epithelial cell transforming 2 (ECT2) in NSCLC and observed that increased ECT2 expression might independently predict poor OS and RFS in LUAD, but not in lung squamous cell carcinoma." (PMID 29746588, 2018).
glioblastoma (7 papers, 2011 to 2023). The most malignant astrocytic tumor (WHO grade IV). "ECT2 (epithelial cell transforming 2) is a known oncogene that is upregulated in various cancer types and associated with poor prognosis in glioblastoma and astrocytoma." (PMID 28806777, 2017). "The expression of the three GEFs Ect2, Trio, and Vav3 is elevated in the glioblastoma as compared to lower-grade glioma, and the depletion of any of the three is sufficient to reduce migration and invasion of glioblastoma." (PMID 32089990, 2020). "Similarly, Ect2 is also overexpressed and mislocalized in glioblastoma multiforme (GBM) compared to normal brain tissue and although GBMs respond to full course radiation, they tend to recur." (PMID 21373644, 2011). "ZW10 interacting kinetochore protein (ZWINT) and Epithelial cell transforming 2 (ECT), both mitotic checkpoint proteins, have been shown to contribute to poor prognosis across multiple cancer types including glioblastoma." (PMID 35948941, 2022).
non-small cell lung carcinoma (7 papers, 2011 to 2023). A group of at least three distinct histological types of lung cancer, including non-small cell squamous cell carcinoma, adenocarcinoma, and large cell carcinoma. "The output from the cBioPortal database revealed that ovarian epithelial tumor, non-small cell lung cancer, and cervical cancer were the top three human tumors that experienced genetic alterations in ECT2, with alteration frequency approximately between 16 and 24%." (PMID 37106813, 2023). "In particular, ECT2 acts as a nuclear GEF for RAC1 and drives tumor initiation of non-small-cell lung carcinoma through regulating rRNA synthesis." (PMID 32929379, 2020). "In non-small cell lung cancer, FXR1 is overexpressed in the tissues and cells, silencing of FXR1 exhibited reduced cell growth and elevated cell apoptosis ratio via destabilizing ECT2 mRNA." (PMID 30691465, 2019). "Recently, Ect2 has been shown to be overexpressed and mislocalized to the cytoplasm of primary non-small cell lung carcinoma (NSCLC) tumor cells as well as NSCLC cell lines, but not primary normal lung epithelia." (PMID 21373644, 2011).
ovarian carcinoma (7 papers, 2013 to 2025). A malignant neoplasm originating from the surface ovarian epithelium. "This region contains the MECOM, SnoN/SKiL, and ECT2 genes all of which have been implicated in ovarian cancer pathogenesis." (PMID 23289505, 2013). "Also, ECT2 has been proposed as a diagnostic and prognostic biomarker in cervical and ovarian cancer." (PMID 39552710, 2024). "Ovarian cancer is a malignancy with the second-highest frequency of ECT2 amplification, and ECT2 is also overexpressed at the mRNA level." (PMID 40655948, 2025). "In ovarian cancer, ECT2 was reported to stimulate cellular transformation by acting as a RhoGEF specifically within the nucleus." (PMID 37106813, 2023). "The ECT2 domain includes three tandem BRCTs, which may be one of the important mechanisms by which ECT2 is involved in the occurrence and development of ovarian cancer." (PMID 40655948, 2025). "And through the correlation analysis of the expressions of ECT2 and RHOA, ROCK1, and ROCK2 in ovarian cancer samples in TCGA database, it was found that the expression of ECT2 was significantly positively correlated with RhoA, ROCK1, and ROCK2." (PMID 40655948, 2025). "This article reviews the roles of ECT2 and RhoA/ROCK signaling pathways in ovarian cancer, cervical cancer, and endometrial cancer, and summarizes and discusses the research progress of downstream molecules, transduction pathways, and mechanisms related to them." (PMID 40655948, 2025). "Moving to the results of the KM plotter, breast, gastric, and liver tumors demonstrated a negative correlation between ECT2 expression and patient survival in all of the analyzed models, while ovarian cancer showed the same correlation in terms of overall and progress-free survival." (PMID 37106813, 2023).
pancreatic cancer (7 papers, 2016 to 2023). "Epithelial cell transforming 2 (ECT2) was regulated by Yes-associated protein 1 and mediates pancreatic cancer progression and metastasis." (PMID 37604837, 2023). "The biological function of ECT2 in pancreatic cancer had been discussed in our previous work, so we mainly focused on NUSAP1 during subsequent research." (PMID 35483343, 2022). "A similar approach was taken by Long and colleagues to infer ECT2 signalling mechanisms in pancreatic cancer." (PMID 28806777, 2017). "Overexpression of ECT2 also promoted the growth and metastasis of pancreatic cancer cells." (PMID 34367280, 2021).
prostate carcinoma (7 papers, 2020 to 2024). A carcinoma that arises from epithelial cells of the prostate gland. "Only two genes, ANLN and ECT2, were strongly correlated with prostate cancer prognosis and patients tended to have better survival rates when these genes were less active." (PMID 38785827, 2024). "Similarly, the top gene set whose GSAS was different between resistant and sensitive metastatic prostate samples to abiraterone treatment was driven by KNSTRN, ECT2 and RCC2 genes, three genes previously associated with prostate cancer progression." (PMID 38597610, 2024). "The generated graphs illustrated that, in breast, kidney, liver, and prostate cancers, ECT2 was significantly upregulated in tumor tissues versus normal ones, a trend that was kept when we set a comparison between ECT2 expression in tumor tissues versus metastatic ones." (PMID 37106813, 2023).
lung adenocarcinoma (5 papers, 2017 to 2024). A carcinoma that arises from the lung and is characterized by the presence of malignant glandular epithelial cells. "Based on GEPIA database, seven of the top ten co-expressed genes were highly expressed in lung adenocarcinoma (DSC2, SLC2A1, ARNTL2, ERO1L, ECT2, ANLN and LAMC2)." (PMID 32095325, 2020).
triple-negative breast carcinoma (4 papers, 2019 to 2021). An invasive breast carcinoma which is negative for expression of estrogen receptor (ER), progesterone receptor (PR), and human epidermal growth factor receptor 2 (HER2). "For example, ECT2 can regulate the growth of triple-negative breast cancer cells through the intervention of paclitaxel." (PMID 34367280, 2021). "Markers for cell proliferation like Top2a, Birc5, and Mki67 are highly expressed, so are markers for metastasis like Msln, Ect2, and Plk1, which are known to be overexpressed in triple-negative breast cancer (TNBC)." (PMID 32793490, 2020). "Consistently, we found that depletion of the ECT2-Ex5+ isoform (as well as depletion of ZRANB2 or SYF2) did not affect Doxo survival in two triple-negative breast cancer cell lines." (PMID 31943118, 2020).
adenoma (3 papers, 2013 to 2022). A neoplasm arising from the epithelium. "We showed that genes ANLN, CDK1, ECT2, and TNC were associated with adenoma progression to carcinoma, ANLN and PDGFD with development of metastases, while genes ANLN, CDK1, ECT2, and PDGFD were associated with the level of malignancy." (PMID 36362041, 2022). "The genes TNC, CDK1, ANLN, and ECT2 were significantly upregulated in adenoma with early carcinoma when compared to adenoma and can be considered as potential biomarkers for malignant transformation." (PMID 36362041, 2022). "Array data mining found that genes such as Ccnb1, Igfbp3, Nusap1, Pttg1, Racgap1, Top2a, Tpx2, which are associated with the aggressive behaviour of various human tumors, including PAs, and proto-oncogenes such as Ect2, Kit, Kras, Lyn, Ret are up-regulated in rat adenomas." (PMID 23756599, 2013). "Statistically significant results in adenomas include 12.4-fold downregulation of TNC (p ≤ 0.001), 9.4-fold downregulation of TNXB (p ≤ 0.001), and 6.0-fold upregulation of ECT2 (p ≤ 0.001)." (PMID 36362041, 2022). "ANLN, CDK1, ECT2, and TNC were differentially expressed between adenoma and adenoma with early carcinoma." (PMID 36362041, 2022). "We identified statistically significant differences between the adenoma and adenoma with early carcinoma for ANLN (p ≤ 0.001), CDK1 (p ≤ 0.05), ECT2 (p ≤ 0.01), and TNC (p ≤ 0.05)." (PMID 36362041, 2022). "In adenomas with early carcinomas, statistically significant results include TNXB with 7.7-fold downregulation (p ≤ 0.001), 4.4-fold upregulation of CDK1 (p ≤ 0.01), 14.1-fold upregulation of ANLN (p ≤ 0.001), and 26.3-fold upregulation of ECT2 (p ≤ 0.001)." (PMID 36362041, 2022). "ECT2 was identified as overexpressed in adenomas and CRC, elevated nucleated ECT2 correlated with poorly differentiated tumors, a low cytoplasmic to nuclear ratio of ECT2 was associated with poor patient survival and suggests that this gene is a driver of tumor progression." (PMID 36362041, 2022).
astrocytoma (3 papers, 2013 to 2017). "From our results, although both nuclear and cytoplasmic ECT2 expression showed significant grade‐dependent increases in astrocytomas, the nuclear, but not cytoplasmic, ECT2 scores were positively correlated with cytoplasmic Rac1 expression." (PMID 27790861, 2016). "Moreover, Ect2 co-localizes with Rac1 and Cdc42 in the membrane ruffles of migratory astrocytoma cells, and inhibition of Ect2 led to decreased Rac1 and Cdc42 activity, with no change in Rho activity." (PMID 24109588, 2013).
cervical cancer (3 papers, 2023 to 2025). A primary or metastatic malignant neoplasm involving the cervix. "ECT2 and RhoA can be used as potential therapeutic targets for the reversal of tolerance to radiotherapy and chemotherapy for cervical cancer." (PMID 40655948, 2025). "ECT2 is the gene with the highest -fold upregulation in chromosome 3q, making it a good candidate for a driver oncogene in cervical cancer cells." (PMID 40655948, 2025). "ECT2 can mediate a variety of signaling pathways involved in the progression of cervical cancer, and other pathways are still under investigation." (PMID 40655948, 2025). "Some studies have found that after the knockdown of ECT2, the proliferation rate of cervical cancer cells decreases; However, after overexpression of ECT2, the proliferation rate of cervical cancer cells increases." (PMID 40655948, 2025). "Downregulation of ANLN and ECT2 led to predicted repression of cytokinesis of cervical cancer cell lines (p < 0.05)." (PMID 38785827, 2024). "And through the correlation analysis of the expressions of ECT2 and RHOA, ROCK1, and ROCK2 in cervical cancer samples in TCGA database, it was found that the expression of ECT2 was significantly positively correlated with RhoA, ROCK1, and ROCK2." (PMID 40655948, 2025). "ECT2 may be also involved in the occurrence and progression of cervical cancer through this signaling pathway, but no further studies have confirmed this so far." (PMID 40655948, 2025). "It has been proven that ECT2 also promotes cervical cancer progression by regulating the AKT/mTOR pathway, and the expression levels of p-AKT and p-mTOR are also significantly increased in cells overexpressing ECT2, while the opposite is true for underexpressing ECT2." (PMID 40655948, 2025).
esophageal cancer (3 papers, 2017 to 2022). A primary or metastatic malignant neoplasm involving the esophagus. "Knock-down of ECT2 expression resulted in inhibition of tumor growth in both lung and esophageal cancer cell lines." (PMID 28362321, 2017). "Tumor tissue microarray analysis that investigated ECT2 expression in tumors and its prognostic value indicated that this gene is a likely prognostic biomarker and a potential therapeutic target for developing anticancer drugs for lung and esophagus cancers." (PMID 28362321, 2017). "Previous studies demonstrated that ECT2 could promote the growth and invasion of esophageal cancer, which were consisted with our results." (PMID 29108269, 2017). "Additionally, knockdown of ECT2 and ITGA6 expression suppressed esophageal cancer cell growth and proliferation." (PMID 29108269, 2017).
esophageal squamous cell carcinoma (3 papers, 2017 to 2020). Esophageal squamous cell carcinoma (ESCC) is a type of esophageal carcinoma (EC) that can affect any part of the esophagus, but is usually located in the upper or middle third. "High level of ECT2 expression was also associated with poor prognosis in patients with esophageal squamous cell carcinomas." (PMID 29088286, 2017). "The current study demonstrated that ECT2 and other eight candidate genes were correlated to progression and prognosis of esophageal squamous cell carcinoma, which might provide novel insights to the mechanisms." (PMID 29108269, 2017).
liver cancer (3 papers, 2021 to 2024). An epithelial or non-epithelial malignant neoplasm that arises from the liver. "We also found that the hub upregulated genes in this network—MCM3, BUB1B, DLGAP5, DIP5, ECT2—have been linked to liver cancer according to wide literature reports." (PMID 39628446, 2024). "GSEA results showed that ECT2 was significantly associated with pathways linked to liver cancer-related pathways and the PID_PLK1 pathway." (PMID 33558466, 2021).
osteosarcoma (3 papers, 2021 to 2024). A usually aggressive malignant bone-forming mesenchymal neoplasm, predominantly affecting adolescents and young adults. "In conclusion, the current results show that calycosin has pharmacological effects against osteosarcoma (OS) by both in vivo and in vitro inhibiting the neoplastic IκBa/ECT2 pathway and suppressing the neoplastic miR‐223‐IκBα pathway, both of which are connected to triggering death in tumor cells." (PMID 38230908, 2024). "TOP2A and ECT2 were found up-regulated in osteosarcomas associated with lung metastases as compared with non-metastatic bone tumors." (PMID 36153320, 2022).
renal cell carcinoma (3 papers, 2020 to 2021). "Functionally, upregulation of ECT2 promoted the tumor progression of renal cell carcinoma." (PMID 34367280, 2021).
bladder cancer (2 papers, 2010 to 2016). "The smoking-related protein HSP90AA1 and DNA methylation of ECT2 mediate the progression from stage 1 bladder cancer cells to metastasis in stage 4 bladder cancer." (PMID 27034531, 2016).
nasopharyngeal carcinoma (2 papers, 2024). A carcinoma arising from the nasopharyngeal epithelium.
ovarian tumors (2 papers, 2013 to 2020). "ECT2 encodes a transforming cell cycle regulator protein highly expressed in ovarian tumors." (PMID 23289505, 2013).